IL1B (interleukin 1 beta)
Diseases named in the same sentence as IL1B in open-access papers (continued):
Sharing a sentence is not in itself a finding about the gene and the disease.
colitis (continued). "In HFD animals, the exercise significantly accelerated the healing of colitis, raised the plasma levels of IL-6 and irisin, downregulated the expression of IL-1β, TNF-α, and Hif1α, and significantly decreased the plasma IL-1β, TNF α, TWEAK, and leptin levels." (PMID 25684862, 2015). "In the present study, we further demonstrate that local TNF-α and IL-1β expressions are decreased after HQT or mesalazine treatment in rats with TNBS-induced colitis." (PMID 26347453, 2015). "In this innate immune model of colitis, Tpl2−/− mice experienced milder colitis compared to wild type mice with reduced production of inflammatory cytokines IL-1α, IL-1β, IL-6, and IL-17, as well as reduced production of the anti-inflammatory cytokine IL-10." (PMID 25781948, 2015). "In our study, the expression of the Th1-type cytokines IFN-γ, TNF-α and IL-1β in the colon is down-regulated in response to MMF after TNBS-induced colitis in our IBD mouse model, after both three and 10 days." (PMID 26561804, 2015). "Considering that TNBS instillation in mice induced an intense colon inflammation, we analyzed the local secretion of IL-1β, IL-6 and TNF-α." (PMID 25853847, 2015). "These protective effects were only achieved with administration of a low dose of IL-1β, and only when given 24 h before induction of colitis." (PMID 25071778, 2014). "A p38 inhibitor suppressed inflammation in DSS-induced colitis model by reducing mucosal IL-1β and TNF-α levels." (PMID 24830946, 2014). "Overproduction of proinflammatory cytokines, including TNF-α, IL-1β, and IL-6, is observed in several animal colitis models." (PMID 24995035, 2014). "To elucidate the mechanism underlying the therapeutic effect of hHGF, we studied the expression of TNF-α and IL-1β in the colon and evaluated the inflammation and crypt scores at days 4, 7, 10 and 14 of the experimental colitis model." (PMID 24604303, 2014). "A study of colitis in a mice model has shown RVs from the D-series can reduce production of pro-inflammatory cytokines such as TNF-α and IL-1β, similarly to the effects RV-E1 demonstrates in colitis." (PMID 24580770, 2014). "A bioflavonoid derived from the seeds of Garcinia kola, kolaviron, exhibits an anticolitis effect by reducing nitric oxide, myeloperoxidase activity, TNF-α, and IL-1β in DSS-induced colitis mice." (PMID 25045208, 2014). "In this study, we found that the mRNA expression of IL-1β was inversely correlated with syndecan-1 in the intestinal mucosa of DSS-induced colitis." (PMID 23874391, 2013). "This increase in severity of colitis observed in 5-HTP treated groups was also resulted in increased levels of colonic IL-1β and IL-6." (PMID 24015275, 2013). "DSS induced colitis also caused a 2-fold increase in the expression of TNF-α mRNA and 4- and 5- fold increases in the expression of IL-6 and IL-1β, respectively." (PMID 23469045, 2013). "Infected Nlrp3−/− mice developed severe colitis; IL-1β treatments reduced colonization, abrogated dissemination of bacteria to mesenteric lymph nodes, and protected epithelial integrity of infected Nlrp3−/− mice." (PMID 24312491, 2013). "We found that syndecan-1's mRNA and protein expression in the colonic mucosa of DSS-induced colitis mice was gradually decreased, while the levels of IL-1β and the free syndecan-1 ectodomain in the serum were increased." (PMID 23874391, 2013). "To investigate the role of inflammatory factors in DSS-induced colitis, we determined the mRNA levels of IL-1β and IL-10 in the intestinal mucosa by qRT-PCR." (PMID 23874391, 2013). "We then evaluated the expression of TNF-α, IL-1β, and IL-6 from each fraction to determine their relative contributions to mesenteric cytokine expression during acute colitis." (PMID 24386254, 2013). "IL-10 is an important anti-inflammatory factor secreted by mononuclear cells and macrophages in colitis, which can suppress inflammatory reaction and decrease the secretion of pro-inflammatory cytokines such as IL-1β and TNF-a." (PMID 23874391, 2013).
colitis (continued). "The increased IL-1β appeared close to plateau by day 6 with the distribution seemingly shifted to the proximal colon, which is line with induced colitis present after 5 days of DSS challenge." (PMID 23577872, 2013). "Reduction in the severity of DSS colitis was associated with significantly lower MPO activity, as well as reduced IL-1β, IL-6 and IL-17 production in IL-13−/− mice." (PMID 24015275, 2013). "The leukocyte infiltration into the mucosa and submucosa of the small intestine of mice with colitis at 6 DPI was associated with increased concentration of IL-6, IL-12p70, IL-10, IL-22 MCP-1 and TNF-α, IL-1β, MPO but lower concentration of IL-17A." (PMID 24167594, 2013). "In this study, we found that LMWH downregulated the levels of IL-1β and IL-10 in colitis mucosa, reduced the shedding of syndecan-1, and ameliorated colitis induced by DSS." (PMID 23874391, 2013). "IL-1β is secreted by macrophages and its activation within the mucosa and sub-mucosa induces and perpetuates human colitis." (PMID 24204877, 2013). "In contrast, the oral FSG treatment significantly decreased MIF expression 24 h after colitis (p<0.05) and IL-1β levels on days 1 and 3 post-TNBS (p<0.05; p<0.01 respectively) compared to corresponding values obtained in colitic rats." (PMID 23166707, 2012). "TNBS-induced colonic inflammation in mice is a commonly used chemically induced model that features up-regulation of pro-inflammatory cytokines (IL-1β, IFNγ, TNFα, IL-12, IL-17A)." (PMID 22461841, 2012). "Our study shows that FSG treatment prevented the colitis-induced increase in IL-1β and MIF in the rat colon." (PMID 23166707, 2012). "Further, anti-mouse IL-1β antibody suppressed clinical symptoms in murine acute DSS-induced colitis." (PMID 23209802, 2012). "In acute TNBS rat colitis model, a decreased neutrophil influx and IL-1β production as well as an enhanced apoptosis of colonic mucosa was observed following Resveratrol treatment." (PMID 21151942, 2010). "In colitis tissue, the expression of IL1β increases in immune-challenged cells due to the activation of nuclear factor kappaB (NFκB)." (PMID 20423518, 2010). "The importance of IL-1β in the development of inflammatory cachexia was previously reported in experimental models of chronic inflammatory diseases, such as cancer or colitis, in which neutralization of IL-1β attenuated inflammatory anorexia." (PMID 20953376, 2010). "The increase of IL-1β in the colitis group was significantly decreased in all groups except in the B. infantis DSM 15158 group." (PMID 17069659, 2006). "Similarly, in colon tissue from a human with active colitis, EPICERTIN significantly upregulated CSF2 and tissue repair-associated genes while downregulating proinflammatory genes (IL1B, IL6ST)." (PMID 41651223, 2026). "In a DSS-induced murine model of colitis, matrine treatment mitigated disease symptoms, reduced key inflammatory markers (IL-1β, TNF-α, IL-6) and oxidative stress indicators (including ROS), and restored bile acid homeostasis by upregulating transporters (MRP3 and MRP4) and bile acid receptor FXR." (PMID 41882686, 2026). "Interleukin 6 and IL-1β play vital roles in the pathophysiology of inflammatory diseases by accelerating neutrophil recruitment and inhibiting T cell differentiation, which are used to monitor the occurrence and development of colitis." (PMID 40431130, 2025). "We observed increased levels of pro-inflammatory factors (IL-1β, TNF-α, and IL-17) in the colon tissues of KOIEC mice compared to those in WT mice during DSS-induced colitis, via the enzyme-linked immunosorbent assay (ELISA) and quantitative real-time PCR (qPCR)." (PMID 40089459, 2025). "Since sorbitol enhanced the expression of Il1b, which is mainly produced from M1 macrophages, we assessed whether the exacerbation of experimental colitis by sorbitol was interleukin-1β (IL-1β) dependent." (PMID 40678521, 2025).
colitis (continued). "For instance, Lactobacillus rhamnosus 1.0320 combined with inulin can alleviate colitis caused by DSS, reduce the disease activity index score of colon tissue damage, and increase IL-10 expression while downregulating IL-1β, IL-6, TNF-α, and myeloperoxidase (MPO)." (PMID 40521353, 2025). "However, the detection of the barrier protein Occludin and inflammatory factors TNF-α and IL-1β indicate the occurrence of colitis in the DSS + ABX mice." (PMID 40647020, 2025). "Rutin can decrease IL-1β levels in experimental animals induced with colitis." (PMID 40395731, 2025). "Furthermore, examination of IL-1β, one of the most critical pro-inflammatory factors for DSS-induced colitis, uncovered that IL-1β was predominantly detected in the distal colon both in the mucosal layer and in the thickened submucosal layer." (PMID 41277366, 2025). "Our study showed that PA improved colitis in mice, as evidenced by improvements in disease-related indicators, including weight loss, DAI scores, pathological manifestations, and levels of pro-inflammatory mediators (IL-1β, IL-6, TNF-α)." (PMID 40969742, 2025). "Mechanistic insights from previous studies have also highlighted impaired production of type I and III interferons in XLA patients following enteroviral infections, as well as dysregulated IL-1β signaling and NLRP3 inflammasome hyperactivation in BTK-deficient colitis models." (PMID 40963632, 2025). "In UC-related studies, targeting IL-1B effectively alleviates colitis in mice." (PMID 40620701, 2025). "Additionally, analysis of colitis samples suggests that higher expression of PTX3 and IL-1β took place in some cohorts of colitis samples compared with the controls." (PMID 40230417, 2025). "Similarly, hucMSC-derived exosomes deliver miR-378a-5p, which also inhibits NLRP3 activation, reduces the release of IL-1β, and alleviates colonic inflammation." (PMID 41012464, 2025). "Moreover, our DSS-induced colitis mice increased the levels of proinflammatory cytokines including IL-1β, TNF-α, IFN-γ, IL-17, and IL-18, which have been shown to increase in IBD patients." (PMID 40224484, 2025). "In addition, TNF-α and IL-1β levels were lower in betanin-supplemented rats compared to other colitis-affected rats." (PMID 41515203, 2025). "Additionally, the Rnf128−/−→Rnf128+/+ group presented increased macrophage infiltration, fewer Ki67-positive cells and higher levels of proinflammatory cytokines (Il-1β and Tnf-α) in the serum of the mice with colitis than the Rnf128+/+→ Rnf128+/+ group." (PMID 39809743, 2025). "Specifically, the expression pattern of c‐Jun changed from focal on day 7 to uniform on day 11, and Kim‐1 and Il‐1β transcription were elevated only at the later time point at day 11, indicating progression of the kidney injury and inflammation secondary to colitis and gut‐barrier dysfunction." (PMID 40018982, 2025). "Similarly, indole-3-carbinol (an indole resulting from the hydrolysis of glucobrassicin) was able to significantly decrease the intestinal expression of NF-κB and several inflammatory factors such as TNF-α, IL-1β, IL-6, and IL-8 in mice with colitis." (PMID 40508374, 2025). "Besides, SIRT5 desuccinylates K311E of PKM2, promotes its nuclear entry and binds to the promoter of the IL-1β gene to form a PKM2-HIF1α complex, reduces IL-1β production, and inhibits the pro-inflammatory response of macrophages in colitis." (PMID 39979670, 2025). "The synbiotic FCT (fermented milk with L. gasseri 505 and C. tricuspidata) has demonstrated concurrent upregulation of MUC2, TFF3, and tight junction proteins (occludin, ZO-1), along with significant downregulation of TNF-α, IFN-γ, IL-1β, IL-6, and iNOS/COX-2 in colitis-associated cancer models." (PMID 41395459, 2025).
colitis (continued). "A similar study by Xu and team revealed that the hucMSC-exosome relieves macrophage pyroptosis to ameliorate murine colitis by inhibiting caspase 11 activation and reducing the release of IL-1β, IL-6, and caspase 11.HucMSC exosomes repaired the distorted structure of the colon epithelium." (PMID 40534879, 2025). "Additionally, the UAF1 inhibitor demonstrated a significant suppression of the levels of inflammatory markers (TNF-α, IL-6, IL-17, and IL-1β) in the colon tissue of colitis mice (P < 0.05 and P < 0.01)." (PMID 39966502, 2025). "In fact, patients with colitis had elevated levels of IL-1β, IL-6, and TNF-α." (PMID 40238292, 2025). "Moreover, active IL-1β and IL-18 levels are associated with increased FLC, along with more severe colitis damage and tumor formation." (PMID 40806736, 2025). "Many studies have shown that CB or AKK can play a protective role in mouse colitis by regulating some key components related to the inflammatory response, such as pro-inflammatory cytokines (IL-1β, IL-6, and TNF-α) and anti-inflammatory cytokines (IL-4 and IL-10)." (PMID 39840995, 2025). "Lipopolysaccharide-induced polarization of pro-inflammatory macrophages biases tripartite-motif protein (TRIM21)-SIRT5 interactions toward activation of TRIM21 and degradation of SIRT5, leading to increased interleukin-1beta (IL-1β) production in vitro and in vivo, thereby aggravating colitis." (PMID 39979670, 2025). "In another colitis model induced with oral dextran sulfate, EO given by gavage for 11 days alleviated the clinical findings in mice and significantly decreased the gene expression levels of IL-1β, TGFβ1 and IL-6 in colon tissue." (PMID 40233022, 2025). "Additionally, anti‐CD40‐induced colitis mice showed significantly higher levels of mRNA expression of proinflammatory cytokines IL‐1β, IFNγ, and TNFα in colonic mucosa when compared to controls." (PMID 40410944, 2025). "In line with our hypothesis, it has been shown that Nrf2 prevents LPS-induced transcriptional upregulation of several pro-inflammatory cytokines, such as IL-6 and IL-1β, whose production is increased in Nrf2−/− mice with dextran sulfate-induced colitis." (PMID 40002358, 2025). "SIRT5 deacetylates Lys351 of TRIM21, inhibiting the production of IL-1β and preventing colitis." (PMID 39979670, 2025). "GPX8-deficient macrophages show a significant increase in IL-1β production under LPS stimulation, and C57BL/6 mice that received transplants of GPX8-deficient macrophages displayed a phenotype indicative of exacerbated colitis." (PMID 40273141, 2025). "In mouse models of colitis, the administration of GLP-1 has been reported to alleviate colonic inflammation and colon damage by reducing the expression of pro-inflammatory cytokine IL-1β, increasing goblet cell numbers, preserving intestinal epithelial architecture, and expanding intestinal crypts." (PMID 40723884, 2025). "Additionally, Rhy lowered serum levels of inflammatory cytokines IL-6, TNF-α, CXCL1, and IL-1β in colitis mice." (PMID 41031160, 2025). "Additionally, AhR∆IEC colitis mice showed significantly higher levels of mRNA expression of proinflammatory cytokines IL‐1β, IFNγ, and TNFα in colonic mucosa when compared to WT mice with colitis." (PMID 40410944, 2025). "Similarly, in a study involving mice with DSS-induced colitis, Bifidobacterium pseudolongum was found to reduce the mRNA expression levels of pro-inflammatory cytokines (IL-1β, IL-6, IL-10, and TNF-α)." (PMID 40299512, 2025). "Molecular simulation-based stability assessment demonstrated that inulin could primarily target iNOS and may also supplementarily target COX-2 and IL-1β during DSS-induced colitis to reduce the role of these inflammatory mechanisms." (PMID 38760355, 2024).
colitis (continued). "This study found that compared with colitis models induced by DSS, expression levels of NO, TNF-α, IL-1β, and IL-6 were remarkably reduced in the peripheral blood and colon tissues of colitis mice pre-treated by B. tequilensis YB-2, while expression levels of IL-10 and IL-4 significantly increased." (PMID 38998101, 2024). "Daidzein inhibited the expression of IL-6 and IL-1β in mice with DSS-induced colitis." (PMID 39318778, 2024). "Butein, a major constituent of Toxicodendron vernicifluum ameliorated colitis in IL-10(-/-) mice by reducing the colonic inflammatory score by > 50%, reducing the expression levels of IL-6, IL-1β, IFN-γ pSTAT3 and MMP-9, also inhibiting IL-6-induced activation of STAT3 in Colo 205 cells." (PMID 39494333, 2024). "Indeed, immune blockade of IL-1β has shown therapeutic effects in experimental colitis mouse models." (PMID 38791376, 2024). "Moreover, ELISA results revealed that serum IL-1β production was dramatically blocked by administering CQ to mice with DSS-induced colitis." (PMID 39701924, 2024). "The colitis group had higher concentrations of IL-1β than the control group (p < 0.05)." (PMID 39201260, 2024). "Thus, blocking IL-1β and IL-18 would be one of the plausible approaches for the treatment of colitis accompanying pyroptosis." (PMID 38491049, 2024). "Furthermore, eFMT also increased TNF-α and IL-1β expression and NF-κB+CD11c+ cell population in the colon, resulting in colitis." (PMID 38885258, 2024). "Spirulina platensis (SP) and Dunaliella salina (DS) were investigated on acetic acid-induced colon inflammation in rats, and both microalgae demonstrated anti-inflammatory properties by inhibiting the production of proinflammatory cytokines such as IL-1β, TNF-α, and IL-6." (PMID 39195452, 2024). "Moreover, the administration of emodin nanoparticles has been shown to suppress the expression of iNOS, COX2, and IL-1β at both the mRNA and protein levels, thereby preventing the damage caused by DSS-induced colitis." (PMID 39203780, 2024). "High levels of IL-1β may contribute to mucosal injury, immune cell recruitment, and exacerbated inflammatory responses in colitis models." (PMID 39201260, 2024). "In addition, previous studies have shown that Lactobacillus can inhibit the expression of TNF-α and IL-1β in macrophages, thereby alleviates colitis." (PMID 39346650, 2024). "Moreover, D. vulgaris also significantly augmented DSS-induced colitis by exacerbating the damage of gut barrier and the secretion of inflammatory cytokines, for instance, IL-1β, iNOS, and TNF-α." (PMID 39060944, 2024). "The novel RORγt inverse agonist and TGR5 agonist compound 7 (University of Naples) has been shown to provide robust anti-inflammatory activity in mice models of TNBS-induced colitis, reducing TNFα, IL-1β, and IL-6 expression while increasing IL-10 and TGFβ expression." (PMID 38664391, 2024). "In the spontaneous TCRα‐deficient model of colitis, an increase in IL1A and IL1B occurs in young mice (age 4–8 weeks), suggesting that the lack of TCR receptor will consequently lead to an increase in the expression of these cytokines even before there is histological evidence of colitis." (PMID 38992956, 2024). "The results showed ZW3 partially mitigated body weight loss, disease activity index (DAI), colon shortening, and suppressed immune response in colitis mice, as evidenced by the reduction in the levels of the inflammatory markers IL-1β, TNF-α, and IL-6 (p < 0.05)." (PMID 38203732, 2024). "Furthermore, treatment with 10, 25, and 50 mg/kg of syringic acid significantly decreased the tissue levels of TNF-α and IL-1β proteins compared to the UC group in rats with acetic acid-induced colitis." (PMID 38732594, 2024). "Moreover, we evaluated the main pro-inflammatory cytokines (i.e., IL-1β and IL-6) involved in colitis." (PMID 38542183, 2024). "Furthermore, IAA-treated colitis mice exhibited lower levels of pro-inflammatory cytokines including IL-1β and TNFα than the colitis mice." (PMID 39068517, 2024).